CASC2 (cancer susceptibility 2)
Description:
May act as a potential tumor suppressor.
Synonyms: C10orf5
Gene: Long non-coding RNA gene on chromosome 10 (118,046,279 to 118,210,158, forward strand). Ensembl gene ENSG00000177640.
Diseases named in the same sentence as CASC2 in open-access papers:
CASC2 is named in the same sentence as 72 diseases in open-access papers, as found by Europe PMC text mining. Sharing a sentence is not in itself a finding about the gene and the disease. The quoted sentences say what the papers report.
glioma (48 papers, 2014 to 2023). A benign or malignant brain and spinal cord tumor that arises from glial cells (astrocytes, oligodendrocytes, ependymal cells). "The cancer susceptibility candidate 2 (CASC2) lncRNA, which is downregulated gene in various cancers including gliomas, is an important modulator of this pathway." (PMID 33980320, 2021). "In one study, CASC2 overexpression inhibited autophagy and increased glioma stem cell susceptibility to TMZ by the accumulation of lipid peroxides, leading to cell death." (PMID 34316694, 2021). "Our findings indicate that CASC2 was proportionally downregulated in progressed gliomas, while miR-21 expression was inversely associated with CASC2 expression, malignancy grade, and patient survival." (PMID 33120918, 2020). "The key finding of the current study is that downregulation of lncRNA CASC2 and upregulation of miR-21 expression is associated with glioma progression." (PMID 33120918, 2020). "According to a previous study, lncRNA cancer susceptibility candidate 2 (CASC2) could modulate glioma growth and resistance to Temozolomide through phosphatase and tensin homolog (PTEN) pathway by targeting miR-181a." (PMID 34802389, 2021). "Another lncRNA connected to docetaxel resistance in PCa cell lines is cancer susceptibility candidate 2 (CASC2) which has been associated with chemoresistance across various cancer entities, including gastric cancer, glioma, breast cancer, cervical cancer and NSCLC." (PMID 32756406, 2020). "To evaluate whether CASC2 and miR-21 were associated with glioma patient clinical parameters, we divided the samples into “low” and “high” (below and above the gene’s mean expression of all samples, respectively) gene expression groups." (PMID 33120918, 2020). "The tumour suppressor lncRNA CASC2 has been found to be downregulated in glioma tissues and cell lines, which was even more pronounced in patients with advanced clinical stages and those resistant to TMZ." (PMID 37837401, 2023). "For instance, in glioma, the downregulation of CASC2 promotes autophagy through the miR‐193a‐5p/mTOR pathway, resulting in resistance to TMZ." (PMID 37837401, 2023). "Inhibition of autophagy, overexpression of CASC2, or treatment with miR‐193a‐5p inhibitors enhances apoptosis and increases the sensitivity of glioma cells to TMZ." (PMID 37837401, 2023). "LncRNA CASC2 increased the sensitivity of glioma cells to TMZ by upregulating the expression of tumor suppressor PTEN through sponging miR-181a." (PMID 35402226, 2022). "Previous studies have already reported the low expression of CASC2 in glioma, where it acts as a tumor suppressor, resulting in a poorer prognosis and clinicopathological features of glioma patients." (PMID 34408982, 2021). "It has been reported that the low expression of lncRNA CASC2 in glioma serves as a tumor suppressor." (PMID 34408982, 2021). "CASC2 is downregulated in glioma cells and thus increases autophagy through the mTOR signaling pathways." (PMID 33525678, 2021). "Overexpression of CASC2 inhibits glioma malignancy, migration, invasion, and proliferation and induces cell apoptosis via negative modulation of miR-21." (PMID 33980320, 2021). "The expression level of lncRNA CASC2 is downregulated in glioma, which is similar to our previous research that CASC2 serves as a tumor suppressor." (PMID 34408982, 2021). "Overexpression of CASC2 significantly suppresses migration, invasion, and proliferation in glioma through the inhibition of Wnt/β-catenin signaling pathway." (PMID 33980320, 2021). "CASC2 sensitized glioma cells to TMZ and amplified the TMZ-induced suppression of cell proliferation by upregulating PTEN protein expression and downregulating phosphorylated AKT through miR-181a." (PMID 34316694, 2021). "In agreement with our data, CASC2 expression in both studies was shown to correlate with glioma malignancy grade inversely." (PMID 33120918, 2020).
glioma (continued). "Wang and colleagues demonstrated CASC2 and mir-21 reciprocal interaction in glioma cell lines U251 and U87." (PMID 33120918, 2020). "Current knowledge on the involvement and function of lncRNA CASC2 in glioma evidences the availability of a small amount of data from clinical samples." (PMID 33120918, 2020). "In this study, we assessed levels of CASC2 and miR-21 and their interplay in different grades of glioma." (PMID 33120918, 2020). "Consistent with published reports on CASC2/mir-21 interaction in glioma and non-small cell lung cancer cells in vitro, we provide evidence in patient gliomas that CASC2 and miR-21 play antagonistic roles and potentially interact in glioma progression." (PMID 33120918, 2020). "Lower CASC2 and higher miR-21 expression were observed more frequently in patients with advanced tumor stage (IV grade gliomas/glioblastomas) (p < 0.0001)." (PMID 33120918, 2020). "miR-21 was inversely expressed with CASC2 in gliomas and correlated with IDH1wt glioma and poor patient prognosis." (PMID 33120918, 2020). "For example, lncRNA CASC2 functioned as the sponge of miR-181a to regulate glioma progression and the resistance of glioma cells to TMZ by targeting PTEN pathway." (PMID 33298070, 2020). "Gliomas with low CASC2 expression exhibited a high level of miR-21, which was highly associated with the higher glioma grade (p = 0.0001), IDH1 wild type gliomas (p < 0.0001), and poor patient survival (p < 0.001)." (PMID 33120918, 2020). "CASC2 can interact with miR-181a to control glioma cell growth through upregulating PTEN (Phosphatase and Tensin Homolog) pathway." (PMID 32549759, 2020). "Here at the clinical level, we further confirm the recently reported interaction between CASC2 and miR-21 in glioma cell lines." (PMID 33120918, 2020). "A previous study has demonstrated that miR-181a is a direct target of CASC2 and CASC2 negatively regulates miR-181a expression in glioma cells." (PMID 31134151, 2019). "Recent studies have shown that the exogenous upregulation of CASC2 expression can significantly inhibit the growth of undifferentiated endometrial cancer cells and can inhibit the invasion of glioma cells." (PMID 30675129, 2019). "Oncogenic miR-21 can bind to CASC2 in a sequence-specific manner and abrogate CASC2-mediated inhibition of proliferation, migration, and invasion in glioma cells." (PMID 31728180, 2019). "The majority of the glioma-associated lncRNAs serve as “miRNA sponges” to quench miRNA activity (e.g., HOTAIR/miR-326, Gas5/miR-196a-5p, CASC2/ miR-181a and ECONEXIN /miR-411-5p)." (PMID 29458374, 2018). "Later on, CASC2 was unveiled to be a tumor suppressor gene in endometrial, colorectal, lung, and renal cancers and gliomas, probably behaving as ceRNAs by buffering miR-21 and miR-18a, two microRNAs with oncogenic effects." (PMID 30116729, 2018). "The expression of CASC2 is significantly downregulated in glioma, osteosarcoma or cervical cancer tissues and cell lines, and CASC2 expression level is negatively correlated to miR-181a level in glioma tissues." (PMID 30217221, 2018). "CASC2 is negatively downregulated with miR-193a-5p in temozolomide resistant glioma tissues and induce autophagy by controlling mTOR expression to promote drug resistance." (PMID 30693021, 2018). "CASC2 was down-regulated in glioma, and overexpression of CASC2 reduced TMZ-induced autophagy via mTOR up-regulation by targetting miR-193a-5p, thus enhancing the sensitivity of glioma cells to TMZ cytotoxicity." (PMID 30266744, 2018). "In human gliomas, lncRNA CASC2 was able to decrease the expression of miR-21 while miR-21 can also suppress lncRNA CASC2 expression." (PMID 27911852, 2017). "CASC2, a recently found lncRNA, has been proved to be linked with the prognosis of cancer patients and regulate cell growth in NSCLC, glioma, colorectal cancer, gastric cancer, endometrial cancer and renal cell carcinoma cells." (PMID 28199978, 2017).
glioma (continued). "On the other hand, some lncRNAs, such as lncRNA CASC2, have been characterized as tumor suppressors in glioma." (PMID 27104549, 2016). "CASC2 suppresses cell proliferation, migration, and invasion, and promotes cell apoptosis in human gliomas by miR-21." (PMID 26252651, 2015). "The down-regulation of CASC2 was correlated with a shorter survival time in glioma patients." (PMID 35071748, 2022). "CASC2 lncRNA is downregulated in glioma tissues and glioblastoma cell lines." (PMID 34316694, 2021). "Upregulation of CASC2 through autophagy inhibition by buffering miR-193a-5p and regulating mTOR expression could sensitize glioma to TMZ cytotoxicity." (PMID 34178658, 2021). "Previous studies have confirmed that CASC2 functions as a suppressor for glioma and could inhibit glioma cell proliferation." (PMID 34408982, 2021). "Long non-coding RNA CASC2 suppressed malignancy in human gliomas by miR-21." (PMID 33422052, 2021). "However, the roles of CASC2 and its interplay with miR-21 in different malignancy grade patient gliomas remain unexplored." (PMID 33120918, 2020). "When all samples were divided into IDH1 gene mutated (IDH1mut, n = 18) and IDH1 wild-type (IDH1wt, n = 78) gliomas, we observed a tendency of lower expression of CASC2 in IDH1wt (p = 0.053) and highly significant relationship between higher miR-21 expression and IDH1wt gliomas (p < 0.0001)." (PMID 33120918, 2020). "Whether the activity of CASC2 and miR-21 was linked to the clinical progression of gliomas, we examined gene expression in grade II–III and IV gliomas." (PMID 33120918, 2020). "Furthermore, IDH1 wild-type gliomas more frequently had lower CASC2 and higher miR-21 expression (p = 0.037 and p < 0.0001, respectively)." (PMID 33120918, 2020). "Correlation analysis revealed moderate negative association between CASC2 and miR-21 expression in gliomas (r2 = −0.42, n = 83, p < 0.0001)." (PMID 33120918, 2020). "LncRNA CASC2 was reported to be identified as a glioma suppressor gene via miR‐21, while lncRNA XIST is an oncogene that acts as a molecular sponge of miR‐429.39, 40 Among numerous kinds of nonprotein‐coding RNAs, lncRNAs have a key regulatory role in cancer biology." (PMID 30924320, 2019). "In addition, introduction of miR-21 significantly repressed CASC2-mediated inhibition of glioma cell proliferation, migration, invasion and apoptosis, suggesting reciprocal repression between CASC2 and miR-21." (PMID 28187439, 2017). "For instance, CASC2 could restrain glioma cell invasion, migration and proliferation by negatively regulating miR-21 expression." (PMID 28716020, 2017). "Consistent with previous studies in other tumors, the overexpression of CASC2 could inhibit the malignancy of glioma cells through an arrest of proliferation and migration, correspondingly promoting cellular apoptosis." (PMID 28293170, 2017). "Over-expression of CASC2 could target mir-193a and mir-21 and inhibit malignant behavior in glioma." (PMID 35071748, 2022). "CASC2 by inhibiting miR-181a could increase sensitivity to TMZ in glioma." (PMID 34178658, 2021). "Interestingly, TMZ sensitivity was CASC2-dependent in glioma stem cells." (PMID 34316694, 2021). "Moreover, here we show that highly active CASC2 significantly might have suppressed miR-21 levels in IDH1 wild-type gliomas." (PMID 33120918, 2020). "Although the deregulated expression of CASC2 in cancer enhances its tumorigenic properties, however, the literature evidence limits current knowledge on the pathophysiological implications and the roles of CASC2, and its interplay with miR-21 in the pathology of gliomas." (PMID 33120918, 2020). "Interestingly, lncRNA HNF1A-AS1, lncRNA CCND2-AS1, lncRNA CRNDE, lncRNA CASC2 were revealed that promotional effects on cell proliferation via activation of Wnt/β-catenin cascade in osteosarcoma, glioma, colorectal cancer and bladder cancer were documented, respectively." (PMID 29453409, 2018).
glioma (continued). "However, little is known about the role and function of CASC2 in human gliomas." (PMID 28293170, 2017). "In gliomas, lncRNA CASC2 was displayed as an inhibitor of cell growth through negatively modulating miR-21, whereas lncRNA CRNDE induced cell growth and invasion of glioma via modulating mTOR signaling." (PMID 35341001, 2022). "For example, lncRNA CASC2 negatively regulates miR-21 to suppress cell growth of glioma, whereas lncRNA CRNDE promotes glioma cell growth and invasion through mTOR signaling." (PMID 34194477, 2021). "Meanwhile, CASC2 couples with miR‐181a, thereby modulating resistance to Temozolomide (TMZ) and glioma growth via PTEN signaling." (PMID 32913464, 2020). "Here we demonstrate CASC2 acting as a tumor suppressor and likely interacting with miR-21 in IDH1 wild type gliomas." (PMID 33120918, 2020). "Taken together, these observations suggest that CASC2 acts as a tumor suppressor and potentially as a competing endogenous RNA (ceRNA) for miR-21, plays important role in IDH1 wild type glioma pathogenesis and patients’ outcomes." (PMID 33120918, 2020). "LncRNA CASC2 up-regulates the tumor suppressor PTEN through directly inhibiting miR-181a, thus amplify TMZ sensibility of glioma cells." (PMID 29458374, 2018). "The status of CASC2's low expression is positively correlated with advanced tumor grades, shorter survival time, and poorer TMZ response in glioma patients." (PMID 30116729, 2018). "In this regard, recent studies have demonstrated that lncRNAs in gliomas can serve as molecular decoys, which move proteins or RNAs away from a specific location, like a “sponge” to miRNAs (e.g., HOTAIR/miR-326, CASC2/miR-21, XIST/miR-152, and Gas5/miR-222)." (PMID 28293170, 2017). "For example, we found human lincRNAs NAG7, MEG3, PCAT1, CASC2 and LINC00032, which were involved in nasopharyngeal carcinoma, glioma and bladder cancer, prostate cancer, endometrial cancer and melanoma." (PMID 25075616, 2014). "CASC2 over-expression led to more apoptosis and increased expression of E-cadherin (but not N-cadherin) and vimentin in A172 and T98 glioma cell lines." (PMID 35071748, 2022). "In addition, some lncRNAs, such as lncRNA CASC2, TUG1, TSLC1-AS1, have been characterized as tumor suppressors in glioma." (PMID 27104549, 2016). "In addition, the CASC2 gene expression decreased dramatically with rising tumor grade, and the authors concluded that lncRNA ADAMTS9-AS2, HOXA11-AS, and CASC2 are potential biomarkers for glioma prognosis." (PMID 35619711, 2022). "For example, MALAT1 knockdown increased the permeability of the blood‐tumor barrier, which might help to improve tumor penetration with therapeutics, while restoration of CASC2 expression upregulated PTEN and increased glioma sensitivity to TMZ‐based chemotherapy." (PMID 34316694, 2021). "However, as to our knowledge, no studies are demonstrating CASC2 and miR-21 interaction in patient glioma samples and evaluating its clinical relevance." (PMID 33120918, 2020). "Here we screened 99 different malignancy grade astrocytomas for CASC2, and miR-21 gene expression by real-time quantitative polymerase chain reaction (RT-qPCR) in isocitrate dehydrogenase 1 (IDH1) and O-6-methylguanine methyltransferase (MGMT) assessed gliomas." (PMID 33120918, 2020).
gastric cancer (19 papers, 2016 to 2025). A primary or metastatic malignant neoplasm involving the stomach. "Cancer susceptibility candidate 2 (CASC2) is a lncRNA located on chromosome 10q26, which is frequently found to be downregulated in several cancers, such as pancreatic carcinoma, gastric cancer and papillary thyroid cancer." (PMID 31728180, 2019). "Meanwhile, E2F6 suppresses Dnmt3b recruitment to mediate germ-line gene silencing in murine somatic tissues, and downregulates MIR22HG and lncRNA CASC2 participating in laryngocarcinoma and gastric cancer progression, respectively." (PMID 39767802, 2024). "In gastric cancer tissue (n = 67) and cell lines, CASC2 expression was downregulated and low CASC2 level in tissue correlated with the vessel invasion, tumor stage, metastasis, and poor patient survival." (PMID 33120918, 2020). "For instance, significantly diminished expression of lncRNA CASC2 was observed in DDP-resistant gastric cancer tissues and cells." (PMID 32192494, 2020). "In particular, CASC2 acts as a tumor suppressor in endometrial, colorectal, lung, stomach, renal, gastric cancers, and osteosarcomas." (PMID 33120918, 2020). "Exogenous expression of lncRNA CASC2 has been found to enhance DDP sensitivity of gastric cancer cells BGC823/DDP and SGC7901/DDP through sponging miR-19a." (PMID 32192494, 2020). "In gastric cancer cells, CASC2 inhibits the phosphorylation levels of ERK1/2 (Extracellular signal-regulated Kinase 1 and 2) and JNK1 (JUN-N-terminal Kinase 1) to decrease cell proliferation." (PMID 32549759, 2020). "For instance, down-regulation of lncRNA CASC2 promoted tumorigenesis in thyroid carcinoma, and overexpression of lncRNA CASC2 inhibited cell proliferation and angiogenesis in gastric cancer." (PMID 30857524, 2019). "It has been demonstrated that the expression of lncRNA CASC2 was down-regulated and lncRNA CASC2 inhibited the cancer cells proliferation, invasion, migration and viability in osteosarcoma, gastric cancer and esophageal carcinoma." (PMID 30857524, 2019). "Meantime, long non-coding RNA CASC2 suppresses the proliferation of gastric cancer cells by regulating the MAPK signaling pathway." (PMID 28199978, 2017). "In gastric cancer, CASC2 acts as a tumor suppressor, and overexpression of CASC2 could inhibit proliferation, colony formation, migration, and invasion of cancer cells." (PMID 36816357, 2023). "In gastric cancer, CASC2 might serve as a tumor suppressor that suppressed cell proliferation by inactivation of mitogen-activated protein kinase (MAPK) pathway." (PMID 28716020, 2017). "Recent work reported that overexpression of miR-18a could promote cell proliferation in gastric cancer by regulating PIAS3 expression and consequentially increase STAT3 activity, leading to enhanced activation of genes downstream of STAT3 modulated by CASC2-targeting miRNAs." (PMID 27198161, 2016). "Furthermore, POU6F1 was found to upregulate lncRNA CASC2, leading to reduced GSH levels through increased SOCS2-mediated ubiquitination and degradation of SLC7A11, thereby inducing ferroptosis in gastric cancer (GC) cells." (PMID 40403492, 2025). "A tumor suppressive lncRNA, lncRNA-CASC2 was shown to be at lower levels in gastric cancer compared to normal adjacent tissue with additional finding that cisplatin-resistant gastric cells, BGC823 and SGC7901, have decreased levels of CASC2 compared to non-resistant cells." (PMID 35582574, 2019).